SND1 (staphylococcal nuclease and tudor domain containing 1)
Diseases named in the same sentence as SND1 in open-access papers (continued):
Sharing a sentence is not in itself a finding about the gene and the disease.
colorectal cancer (17 papers, 2015 to 2025). A primary or metastatic malignant neoplasm that affects the colon or rectum. "It has been verified that the single nucleotide polymorphism (SNP) of staphylococcal nuclease and tudor domain containing 1 (SND1) rs118049207 is significantly associated with the risk of colorectal cancer." (PMID 35220962, 2022). "Only one SNP, rs118049207, located in the SND1 gene, was significantly correlated with colorectal cancer risk." (PMID 33790968, 2021). "Several studies have illustrated the significant association of SND1 with different types of cancers, including liver, breast, prostate and colorectal cancers and malignant glioma." (PMID 25405367, 2015). "Finally, the SNP rs118049207 located in the SND1 gene was found to associate with colorectal cancer risk in the Chinese population." (PMID 32742460, 2020). "Moreover, another recent study also associated SND1 with m6A modification and showed that SND1 could alter m6A levels in colorectal cancer cell lines." (PMID 34205979, 2021). "SND1, also known as p100 or tudor-SN, is a protein highly expressed in various cancers, including breast, liver, and colorectal cancers." (PMID 39895626, 2025). "Among them, only the SND1 gene rs118049207 contributes to the development of colorectal cancer in the Chinese population." (PMID 32091154, 2020). "The staphylococcal nuclease and Tudor domain containing 1 (SND1) is upregulated in colorectal cancer which leads to the ER mediated degradation of MHC proteins, which could also mediate ICB resistance." (PMID 41463180, 2025). "It is essential that the methylation degree of SND1 was more than 18.1-fold and FBLIM1 was more than 12.4-fold in colorectal cancer to that in the normal control." (PMID 37779184, 2023). "The methylation degree of ZNF471 was more than 2.9-fold, SND1 was more than 14.5-fold, SPOCK1 was more than 5.8-fold, FBLIM1 was more than 11.1-fold, and OTX1 was more than 6.9-fold in colorectal cancer or colorectal adenoma to that in the normal control." (PMID 37779184, 2023). "Hypermethylated genes of ZNF471, SND1, SPOCK1, FBLIM1, and OTX1 were obtained from methylation chip detection and further confirm analysis in colorectal cancer and adenoma compared with normal tissue, which may be promising diagnostic markers of colorectal cancer and colorectal adenoma." (PMID 37779184, 2023). "Five hypermethylated genes including ZNF471, SND1, SPOCK1, FBLIM1, and OTX1 were detected and confirmed in 68 cases of colorectal cancer, 31 cases of adenoma, and 49 cases of normal control group." (PMID 37779184, 2023). "However, all the SNPs including YTHDF2 rs4654320 could not predispose to colorectal cancer, except for one SNP rs118049207 in the SND1 gene." (PMID 34539889, 2021). "In the “Other tumors group” four rearrangements involving BRAF gene were detected (three melanoma: BRAF::CNNM2, BRAF::ERC1, BRAF::MAD1L1 and one pancreatic adenocarcinoma BRAF::SND1), but also one ETV6::NTRK3 (colorectal cancer) and one FGFR3::TACC3 (urothelial cancer)." (PMID 37708140, 2023). "Our results indicated that ZNF471, SND1, SPOCK1, FBLIM1, and OTX1 methylation may be useful in diagnosing colorectal cancer and adenoma." (PMID 37779184, 2023). "Hypermethylated genes of ZNF471, SND1, SPOCK1, FBLIM1, and OTX1 were obtained from methylation chip detection and further confirm analysis in colorectal cancer and adenoma compared with normal tissue, which may be promising diagnostic markers of CRC and colorectal adenoma." (PMID 37779184, 2023).
prostate carcinoma (17 papers, 2015 to 2025). A carcinoma that arises from epithelial cells of the prostate gland. "In prostate cancer, STaphylococcal nuclease and Tudor domain containing 1 (SND1) overexpression is associated with the growth of the disease, and the expression of SND1 is downregulated by miRNA-1224-5p, which is responsible for stopping the advancement of cancer." (PMID 39512820, 2024). "Thus, the interaction of Sam68 with SND1 in prostate cancer cells leads to a synergic effect with Sam68 on variant exon inclusion in CD44 mRNA." (PMID 38106992, 2023). "Conclusively, SND1 has been suggested as a promising diagnostic biomarker in prostate cancer." (PMID 34809722, 2021). "Studies focused on prostate cancer have identified SND1 as an efficient diagnostic marker." (PMID 25405367, 2015). "ERG promoted nuclear localization of AEG-1/SND1, which promoted cell proliferation and the deletion of SND1-reduced tumor burden in an ERG-overexpressing mouse prostate cancer model." (PMID 40282551, 2025). "Collectively, we have found that LNC-565686 can promote the proliferation of prostate cancer cells and inhibit apoptosis by stabilizing the expression of SND1." (PMID 37893001, 2023). "Here, the authors report an interaction between ERG and SND1 as necessary for ERG-driven prostate cancer initiation using preclinical models." (PMID 37973913, 2023). "In mice, prostate-specific Snd1 deletion reduces cancer growth and tumor burden in a prostate cancer model (PB-Cre/Ptenflox/flox/ERG mice), Moreover, we find a significant overlap between prostate transcriptional signatures of ERG and SND1." (PMID 37973913, 2023). "The overexpression of staphylococcal nuclease and Tudor domain containing 1 (SND1) is in favor of prostate cancer progression, and miRNA-1224-5p down-regulates SND1 expression in triggering cancer elimination." (PMID 35773731, 2022). "In prostate cancer, transcriptional coactivator staphylococcal nuclease and tudor domain containing 1 (SND1) promotes the recruitment of Sam68 onto CD44 pre-mRNA, suggesting the significance of transcription-coupled RNA splicing events in cancer." (PMID 32106418, 2020). "Knocking down SND1 reduced proliferation of prostate cancer cells demonstrating the importance of SND1 in maintaining prostate cancer viability." (PMID 25405367, 2015). "SND1 also promotes prostate cancer development by positively regulating CD44 alternative splicing, allowing inclusion of variable exon v5 that is known to be pro-oncogenic." (PMID 25405367, 2015). "Knockdown of SND1, or Sam68, reduced proliferation and migration of prostate cancer cells." (PMID 38106992, 2023). "In addition, the circ_0004087/SND1/MYB/BUB1 axis was reported to modulate the error mitosis correction mechanism in prostate cancer cells." (PMID 36803376, 2023). "Following studies revealed that circ_0004087 could interact with SND1 to facilitate DTX chemoresistance of prostate cancer by promoting the mitosis error correction function of CPC." (PMID 35659274, 2022). "Moreover, SND1-knockdown in the prostate cancer cell line PC3, using Small interfering RNA (siRNA), was correlated with diminished cell growth." (PMID 34809722, 2021). "In 174 prostate cancer patients, SND1 levels correlated with histological grade of the tumor." (PMID 25405367, 2015). "In prostate cancer cells, the AEG-1/SND1 complex recruited the oncogenic ETS-domain transcription factor ERG via the Tudor domain of SND1." (PMID 40282551, 2025). "In nude mice xenograft studies, siRNA-mediated inhibition of SND1 abrogated and overexpression of SND1 increased growth of human HCC and prostate cancer cells." (PMID 25965817, 2015). "SND1 is identified as an interacting partner for SAM68, a prooncogenic RNA binding protein that is upregulated in prostate cancer and supports cellular proliferation." (PMID 25405367, 2015).
prostate carcinoma (continued). "SND1 protein levels were comparable to α-methylacyl-coA racemase (AMACR) protein levels, a currently employed marker protein for prostate cancer diagnosis." (PMID 25405367, 2015). "In order to further explore the effects of LNC-565686 and SND1 on prostate cancer cells, we knocked down LNC-565686 and SND1 in prostate cancer cells, and verified using CCK8 and flow cytometry and western blot for the detection of apoptosis-related indicators." (PMID 37893001, 2023). "SND1 regulates the error mitosis correction and DTX chemoresistance in prostate cancer cells." (PMID 37885030, 2023).
colon cancer (14 papers, 2010 to 2023). "Here we have shown that certain cancer drugs are more effective in colon cancer cells when the expression of a protein called SND1, implicated in regulation of stress responses, is prevented in those cells." (PMID 35804872, 2022). "Overexpression of SND1 in colon cancer cells caused down-regulation of APC and activation of the Wnt signaling pathway as a consequence, without altering APC mRNA levels." (PMID 20957089, 2010). "Inhibiting SND1 can enhance the sensitivity of colon cancer cells to navitoclax by upregulating the levels of miR-1-3p." (PMID 37907984, 2023). "Snd1 is overexpressed in several cancers including prostate, hepatic, and colon cancer and B cell malignancies, and several functional roles have been assigned for Snd1 in promoting tumorigenesis and cancer growth." (PMID 37151849, 2023). "The inhibition of SND1 can increase the expression level of miR-1-3p in colon cancer cells and enhance the sensitivity of tumor cells to the Bcl-2 family inhibitor navitoclax." (PMID 37907984, 2023). "This block of SND1-microRNA interaction reduces the resilience of colon cancer cells and thus sensitizes them to cancer treatment." (PMID 35804872, 2022). "Score of IHC staining for the expression of SPT6, SND1, and hTERT based on clinical tissue samples from patients with colon cancer." (PMID 33305480, 2021). "Immunofluorescent experiments also demonstrated the colocalization of SPT6 and SND1 in different colon cancer cells, further proving the possibility of their interaction." (PMID 33305480, 2021). "In colon cancer, SND1 overexpression significantly accelerated cell proliferation in the exponential growth phase." (PMID 34378960, 2021). "We established such a model by applying AOM/DSS induction to further investigate the synergy effect of SPT6 and SND1 on the expression of hTERT during colon cancer progression." (PMID 33305480, 2021). "Next, we explored the synergy produced by SPT6 and SND1 in regulating hTERT expression and colon cancer progression." (PMID 33305480, 2021). "Herein, at least based on the in vitro study, we concluded that SPT6 synergized with SND1 to co‐regulate hTERT expression and to be further involved in colon cancer progression." (PMID 33305480, 2021). "Besides, SND1 knockdown reversed the changes of the transcriptional activity of hTERT, the expression of hTERT, cell viability, tumorsphere‐forming ability and the expression of stemness‐associated markers in colon cancer cells mediated by SPT6 overexpression, and vice versa." (PMID 33305480, 2021). "AEG-1 and SND1 co-expression negatively correlated with postoperative overall survival and positively correlated with mortality (p = 0.009) in cox multivariate analysis, strongly indicating that AEG-1 and SND1 can serve as prognostic factors for colon cancer." (PMID 33671513, 2021). "Through IP‐MS assay using one normal colon cell line and four colon cancer cell lines, we identified some factors cooperating with SPT6 specifically in colon cancer cells and one of them was SND1." (PMID 33305480, 2021). "Previous data suggest early upregulation of SND1 in colon cancer and its potential contribution to early colon carcinogenesis, mainly as a key regulator of colon cancer-development mediators such as β-catenin and APC." (PMID 34809722, 2021). "Consistently, SND1 overexpression was visualized by IHC in chemically induced colon cancer tumors in a rat model but also in precancerous lesions." (PMID 34809722, 2021). "Score of IHC staining for the expression of SPT6, SND1, and hTERT based on tissue samples from mouse with colon cancer." (PMID 33305480, 2021). "Altogether, these results not only demonstrate the oncogenic role of SND1 in colon cancer cells by transcriptionally regulating hTERT, but also uncover the potential synergy between SND1 and SPT6 in co‐regulating hTERT." (PMID 33305480, 2021). "SND1 can promote colon cancer cells proliferation by suppressing APC and activating telomerase." (PMID 37885030, 2023).
colon cancer (continued). "Thus, these in vivo data from CRC tissues collectively demonstrated the possibility that SPT6 cooperates with SND1 to regulate the expression of hTERT and to be further involved in the development of colon cancer." (PMID 33305480, 2021). "Furthermore, through Pull‐down assay, we observed the alleviated binding of SND1 at the promoter of hTERT when SND1 was knocked down, indirectly demonstrating the transcriptional regulation of SND1 on hTERT in colon cancer cells." (PMID 33305480, 2021). "SND1 downregulates adenomateous polyposis coli protein levels by post-transcriptional modification, without altering the mRNA levels of this gene, as reported in colon cancer." (PMID 25405367, 2015). "To investigate the function of SND1 in epithelial cancer cells, we created stable SW480 colon cancer cell lines where doxycycline treatment conditionally and efficiently silenced SND1." (PMID 35804872, 2022). "Altogether, these findings demonstrated that SND1 functionalizes as an indispensable co‐factor of SPT6 to regulate the expression of hTERT and tumor growth in colon cancer progression." (PMID 33305480, 2021). "Significant correlation was observed in nodal stage, pathological stage and co-expression of SND1 and AEG-1 in colon cancer." (PMID 25405367, 2015). "Immunohistochemical analyses of 196 colon cancer cases establish that cytoplasmic expression of AEG1 and SND1 protein positively correlates with tumor grade and cancer progression, but negatively correlates with post-operative survival of patients." (PMID 25405367, 2015). "SND1, also reported to be a component of RISC, is overexpressed in human colon cancer tissues, even in early-stage lesions." (PMID 20146808, 2010). "In predicting the prognosis of colon cancer, the coexpression of AEG-1/MTDH/SND1 may be a novel distinctive marker." (PMID 25009642, 2014). "In colon cancer tissues, a positive correlation has been identified between AEG-1/MTDH and SND1 expression by immunohistochemical staining; AEG-1/MTDH- and SND1-positive expression has been found to significantly correlate with nodal status, pathological stage and differentiation." (PMID 25009642, 2014). "As to CRC, Dr. Nakagama’s group has demonstrated that Staphylococcal nuclease homology domain 1 (SND1), a component of RISC, is frequently up-regulated in human colon cancers and also chemically-induced colon cancers in animals, as well as in preneoplastic lesions of the colon." (PMID 20957089, 2010). "Furthermore, OS time in colon cancer patients with positive AEG-1/MTDH and SND1 expression is significantly shorter than in those without AEG-1/MTDH and SND1 expression." (PMID 25009642, 2014).
liver cancer (10 papers, 2014 to 2025). An epithelial or non-epithelial malignant neoplasm that arises from the liver. "The GSCA dataset revealed that SND1 is one of the eminently mutated genes in HCC, bearing 1.5% somatic mutation frequency, and SND1 overexpression is predominantly observed in liver cancer." (PMID 40841409, 2025). "Emerging findings have demonstrated that SND1 overexpression is linked to progression and malignancy of various types of cancer, such as colon, breast, prostate, lung, glioma, melanoma and liver cancer." (PMID 29296233, 2017). "More interestingly, the SND1 gene overexpression drastically shortened the survival months in grade III tumors of liver cancer patients." (PMID 40841409, 2025). "To confirm this phenomenon, we evaluated the subcellular localization of SND1 in several liver cancer cell lines using isolated cellular compartments." (PMID 35433434, 2022). "We find that SND1 is present in mitochondria based on mass spectrometry data and verified this phenomenon in different liver cancer cell types by performing organelle subcellular isolation." (PMID 35433434, 2022). "Using isolated cellular compartments from tumor tissues of liver cancer patients, we further found that SND1 was indeed enriched in mitochondria." (PMID 35433434, 2022). "In this study, we found that SND1 promotes liver cancer through PGAM5-mediated Drp1S637 dephosphorylation and mitophagy." (PMID 35433434, 2022). "The benefits, to liver cancer cells, of having elevated SND1 can thus be explained, in part, by its pro-inflammatory and pro-angiogenic roles." (PMID 33768972, 2021). "Simulating ER stress in human liver cancer results in an increase in SND1 promoter activity showing that SND1 has a role in ER stress response." (PMID 32258418, 2018). "Here, we have approached this question by analyzing the transcriptional response of human SND1 gene to pharmacological endoplasmic reticulum (ER) stress in liver cancer cells." (PMID 25494629, 2014). "Finally, Person correlation analysis revealed that SND1 is significantly and positively coexpressed with PGAM5 according to the liver cancer database of TCGA, and SND1 thus positively regulates mitophagy through PGAM5." (PMID 35433434, 2022). "Additionally, the association of SND1 and PGAM5 with liver cancer patients was further determined by prognostic analyses." (PMID 35433434, 2022). "We can speculate that the opposite is also true, when SND1 is upregulated, the G1/S transition may be shortened, and this would help explain one of the characteristics of liver cancer, which is a deregulated cell cycle." (PMID 33768972, 2021). "We provide first evidence that SND1 promoter activity is increased in human liver cancer cells upon exposure to thapsigargin or tunicamycin or by ectopic expression of ATF6, a crucial transcription factor in the unfolded protein response triggered by ER stress." (PMID 25494629, 2014). "In the particular case of liver cancer, SND1 and NF-κB intersect at several points." (PMID 25494629, 2014). "The Tudor domain and α–helix present in SND1 are primarily accountable for reading the STD marks produced by PRMT5, and the further progression of molecular events could drive liver cancer." (PMID 40841409, 2025). "Likewise, Staphylococcal nuclease domain-containing protein 1 (Snd1) localizes to the mitochondria and promotes PGAM5-mediated mitophagy and liver cancer progression." (PMID 39063217, 2024). "The ability of SND1 to help liver cancer cells evade cell death is not limited to its role in stress granule formation and function." (PMID 33768972, 2021). "We assume as a hypothesis a regulatory feed-forward loop between SREBP-2 and SND1 transcription and consequently, the overexpression of SND1 may disrupt cholesterol homeostasis and activate the SREBP-2 pathway in the hepatic cancer cells." (PMID 29296233, 2017).
liver cancer (continued). "Interestingly, the analysis of RNA expression databases (TCGA and GEO) does not support a role for SND1 expression in the clinical progression of liver cancer, but the analysis of protein expression by immunohistochemistry does." (PMID 33768972, 2021).
glioblastoma (8 papers, 2015 to 2024). The most malignant astrocytic tumor (WHO grade IV). "Case 2 contained a mutation in SND1, which has been reported to be involved in glioblastoma and carcinomas of the colon, prostate, and liver." (PMID 27175596, 2016). "TCGA data showed a similar trend of high SND1 expression in human astrocytoma and glioblastoma samples as compared to normal brain." (PMID 25405367, 2015). "Together, our results show that SND1 interacts with the SWI/SNF complex and that the SWI/SNF complex localizes to the TCF7 promoter in glioblastoma cells." (PMID 39169000, 2024). "Immunostaining was used to detect the SND1 expression in tissue samples of 58 TNBC and 10 glioblastomas (GBM) as positive control." (PMID 37885030, 2023). "The SND1 protein level in TNBC tissues from 38 patients with lymph node metastasis (Met) and 20 patients without metastasis (non-Met) were evaluated by IHC, and 10 glioblastomas (GBM) high-expressing SND1 were used as positive control." (PMID 37885030, 2023).